RNY4P37 (RNY4 pseudogene 37)
Gene: Miscellaneous RNA gene on chromosome 18 (46,077,004 to 46,077,099, reverse strand). Ensembl gene ENSG00000252034.
Homologues: Orthologues: chimpanzee Y_RNA (99% identical), macaque Y_RNA (90% identical), guinea pig Y_RNA (86% identical). Paralogues in human: RNY4P19 (91% identical), Y_RNA (91% identical), RNY4 (89% identical), RNY4P7 (89% identical), RNY4P6 (88% identical), Y_RNA (88% identical), RNY4P36 (86% identical), RNY4P25 (85% identical), Y_RNA (85% identical), RNY4P10 (84% identical), RNY4P13 (84% identical), RNY4P14 (84% identical), and 91 more.